AP1G2 (adaptor related protein complex 1 subunit gamma 2)
Description:
May function in protein sorting in late endosomes or multivesucular bodies (MVBs). (Microbial infection) Involved in MVB-assisted maturation of hepatitis B virus (HBV).
Synonyms: G2ad
Tractability: Small molecule: a structure with a bound ligand is known. Antibody: UniProt places it where antibodies can reach, with high confidence. PROTAC: ubiquitination databases record sites on it; its protein half-life has been measured.
Gene: Protein-coding gene on chromosome 14 (23,559,557 to 23,568,070, reverse strand). Ensembl gene ENSG00000213983.
Subcellular location: Golgi apparatus membrane; Cytoplasmic vesicle membrane; Endosome membrane
Pathways (Reactome):
Vesicle-mediated transport: Lysosome Vesicle Biogenesis
Gene Ontology:
Molecular function: protein binding; clathrin adaptor activity
Biological process: Golgi to vacuole transport; vesicle-mediated transport; intracellular protein transport
Cellular component: cytoplasmic vesicle membrane; endosome membrane; Golgi membrane; Golgi-associated vesicle; membrane; transport vesicle; AP-1 adaptor complex; Golgi apparatus; intracellular vesicle; membrane coat; synapse
Genetic constraint (gnomAD): Loss-of-function variants: 82 observed, 98.14 expected, observed/expected ratio (o/e) 0.84, 90% interval 0.7 to 1. The upper end of that interval is the gene's LOEUF score, 1, which puts it in group 4 of 6, group 1 being the genes least tolerant of losing a copy. Missense variants: 952 observed, 1,041.2 expected, observed/expected ratio (o/e) 0.91, 90% interval 0.87 to 0.96. Synonymous variants: 374 observed, 413.8 expected, observed/expected ratio (o/e) 0.9, 90% interval 0.83 to 0.99.
Homologues: Orthologues: chimpanzee AP1G2 (99% identical), macaque AP1G2 (97% identical), dog AP1G2 (90% identical), pig AP1G2 (90% identical), rabbit AP1G2 (89% identical), guinea pig AP1G2 (88% identical), mouse Ap1g2 (87% identical), rat Jph4 (87% identical), tropical clawed frog ap1g2 (59% identical), zebrafish ap1g2 (59% identical), Drosophila melanogaster AP-1gamma (50% identical), Caenorhabditis elegans apg-1 (45% identical). Paralogues in human: AP1G1 (61% identical), AP2A2 (28% identical), AP2A1 (26% identical), AP4E1 (25% identical).
Diseases named in the same sentence as AP1G2 in open-access papers:
AP1G2 is named in the same sentence as 8 diseases in open-access papers, as found by Europe PMC text mining. Sharing a sentence is not in itself a finding about the gene and the disease. The quoted sentences say what the papers report.
bipolar disorder (1 paper, 2023). A disorder of the brain that causes unusual shifts in mood, energy, activity levels and the ability to carry out day-to-day tasks. "Potential candidate genes for bipolar disorder with metabolic syndrome were found in 5 candidate genes (AP1G2, C1orf54, DMAC2L, RABEPK and ZFAND5), all of which have diagnostic significance." (PMID 37860165, 2023).
developmental and epileptic encephalopathy (1 paper, 2023). An epilepsy associated with developmental impairment that may be due to either the underlying etiology or the superimposed epileptic activity, or both. "Additionally, AP1G2 is a linked gene in both Developmental and Epileptic Encephalopathy and Intellectual Developmental Disorder, Autosomal Dominant." (PMID 37860165, 2023).
Esophageal atresia (1 paper, 2023). A developmental defect resulting in complete obliteration of the lumen of the esophagus such that the esophagus ends in a blind pouch rather than connecting to the stomach. "Diseases associated with AP1G2 include Tracheoesophageal Fistula With Or Without Esophageal Atresia and Esophageal Atresia." (PMID 37860165, 2023).
lung carcinoma (1 paper, 2026). "A systematic multi-omics analysis was conducted for the eight AP-1 adaptor complex genes (AP1AR, AP1B1, AP1G1, AP1G2, AP1M1, AP1M2, AP1S1, and AP1S3) to characterize their roles in lung cancer." (PMID 41438582, 2026).
AP1G2 also shares sentences with these, for which no sentence is quoted: cardiovascular disease (1 paper); metabolic syndrome (1); pancreatic cancer (1); sudden cardiac arrest (1).